IL1B (interleukin 1 beta)
Diseases named in the same sentence as IL1B in open-access papers (continued):
Sharing a sentence is not in itself a finding about the gene and the disease.
Stroke (continued). "In the present work, studies have shown that Induction of stroke caused a significant increase in TNF-a, IL-1B, and MDA levels compared to the control group (p < 0.001)." (PMID 34600570, 2021). "During the early hours after the onset of stroke, there are increments of various cytokines such as interleukin-1 beta (IL-1β), interleukin-1 receptor antagonist (IL-1ra), interleukin-6 (IL-6), IL-8, IL-10, and tumor necrosis factor alpha (TNF-α)." (PMID 34072449, 2021). "Post-stroke, chronic metformin treatment has suppressed the expression of ‘M1’-associated genes (CD32, IL1b, CD16) and enhanced the expression of ‘M2’-associated genes (CD206, Arg1)." (PMID 32168831, 2020). "Overexpression of miR-126 in ADSC-derived exosomes further enhanced not only neurogenesis and angiogenesis, but also suppression of microglial activation and TNF-α and IL-1β production after stroke." (PMID 32962207, 2020). "In humans, a preliminary study has shown that a receptor antagonist of IL-1β (IL-1RA) has improved stroke outcome." (PMID 33153204, 2020). "In response to stroke, IL-1β is rapidly upregulated in the blood and brain and exacerbates injury in experimental animal models." (PMID 32503645, 2020). "It is known that there is a positive correlation between inflammatory cytokines (TNF-α, IL-1β, IL-6, etc.)and microglial activity after stroke." (PMID 32922507, 2020). "Together with findings of a detrimental role of IL-1β in experimental stroke models, the use of rhIL-1Ra, such as anakinra, holds promise as a neuroprotective treatment in ischemic stroke patients." (PMID 32503645, 2020). "There is also well-documented evidence indicating that monitoring of TNFα and IL-1β levels can provide some valuable information allowing for diagnosis of stroke in patients with accompanying metabolic disorders and those without such complications." (PMID 31701356, 2020). "We therefore compared parallel tissue sections from two stroke cases stained for IL-1α, IL-1β, IL-1Ra, TNF, TNFR1, and TNFR2." (PMID 32503645, 2020). "For a number of reasons the proinflammatory cytokine interleukin-1beta (IL-1β) is considered a therapeutic target for treatment of ischemic stroke to promote recovery after stroke." (PMID 33275615, 2020). "In conclusion, the decreased release of some pro-inflammatory cytokines (IP-10, TNFα, IL-1β, and IL-12p70) and increased release of IL-10 and IL-8 after ex vivo blood stimulation with LPS are related to poor outcome after stroke." (PMID 31906994, 2020). "Although IL-6 and IL-1β have been reported to be neuro reparative after stroke by promotes post-stroke angiogenesis and reduce glutamate mediated excitotoxic cell death, their neurodestructive roles are widely demonstrated." (PMID 32010477, 2020). "ELISA was used to measure levels of IL-1β in spleen tissue from aged males and females at 72 h after stroke." (PMID 33376583, 2020). "We showed previously that TNF and IL-1β and IL-1α, IL-1β, IL-1Ra are produced by subsets of microglia in experimental stroke." (PMID 32503645, 2020). "The results demonstrated that proinflammatory cytokines TNF-α (p < 0.05), IL-6 (p < 0.001), IL-1β (p < 0.01), IL-17 (p < 0.01), and IL-18 (p < 0.01) were increased in wild-type mice subjected to stroke." (PMID 32450881, 2020). "The studies found that the levels of NLRP3 inflammasome proteins, IL-1β and IL-18 were elevated in stroke patients, and also increased in ipsilateral brain tissues of MCAO C57BL/6J mice and primary cortical neurons exposed to OGD." (PMID 32153398, 2020). "IL-6 (Il6) and IL-1β (Il1b) are two crucial pro-inflammatory cytokines in experimental and human stroke." (PMID 33246465, 2020). "mRNA expression of pro-inflammatory cytokines, including IL-6, TNF-α, and CXCL1, were quickly increased after stroke and peaked at 24 h, whereas IL-1β, COX-2, and MCP-1 levels peaked at 48 h after stroke." (PMID 32867781, 2020).
Stroke (continued). "The mRNA levels of proinflammatory factors, including tumor necrosis factor-α (TNF-α), interleukin-1β (IL-1β) and interleukin-6 (IL-6) were significantly increased 1 to 7 days after stroke." (PMID 32010477, 2020). "Therapeutic hypothermia (TH) inhibited the M1 polarization of microglia and reduced the expression of inflammatory factors such as TNF-α, IL-1β, and iNOS in stroke mouse model." (PMID 33381263, 2020). "Our findings show that IL-1β is significantly elevated in cerebral thrombi in contrast to the plasma of stroke patients and healthy controls." (PMID 33569001, 2020). "To evaluate the inflammatory responses of BDMP injection and Lactadherin treatment in stroke mice, we measured the expression of leukocytes, microglia/macrophages, neutrophils, IL1β, IL6, and TNFα in the cortex and striatum of IBZ." (PMID 31993045, 2019). "In stroke, brain IL-1α expression precedes that of IL-1β and occurs predominantly in microglia localized to focal neuronal and BBB injury in this acute period." (PMID 31727174, 2019). "The activation of NLRP3 inflammasome was critical for IL-1β release in multiple sclerosis (MS), stroke, and Alzheimer’s disease." (PMID 31142341, 2019). "The role of IL-1β in promoting human CAD was highlighted by the recently concluded CANTOS trial, showing that anti-IL-1β therapy met the primary endpoint, a reduction in a composite of heart attack, stroke and cardiovascular death." (PMID 31366948, 2019). "In contrast to TNFα and IL-1β, IL-6 mainly has neuroprotective effects and plays a major role in body temperature regulation in stroke patients." (PMID 31544811, 2019). "The large majority of studies have focused on the role of IL-1beta (β) (main released isoform) and demonstrated that interleukin-1 beta isoform (IL-1β) is a primary mediator of central and peripheral inflammation after stroke." (PMID 31727174, 2019). "Our findings are consistent with a previous study revealing reduced IL-1β expression in stroke mice that received hypothermia therapy." (PMID 31644666, 2019). "The IL-1β level was significantly higher in patients with stroke than in healthy volunteers (p<0.01)." (PMID 31644666, 2019). "Expression levels of NLRP3 and NLRP1, as well as cleavage products of caspase‐1, IL‐1β, and IL‐18, were shown to be elevated in postmortem brain tissue of stroke patients." (PMID 31015277, 2019). "The incubation of aortic rings from stroke-prone, spontaneously hypertensive rats with IL-1β for 1 h significantly increases contractility via the activation of cyclooxygenase- and Src-kinase-related signaling pathways." (PMID 31817997, 2019). "Neuroinflammation plays a crucial pathological role in stroke, and IL‐1β has been identified as a key cytokine in stroke pathology." (PMID 31015277, 2019). "Some studies have shown that I/R significantly increased levels of NLRP1, NLRP3 inflammasome proteins, IL-1β, and IL-18 in the ipsilateral brain tissues of I/R-model mice or stroke patients." (PMID 31174550, 2019). "Inflammatory cytokines such as TNF-α, IL-1β, and IL-6 play a role in the induction and pathoprogression of stroke." (PMID 30046341, 2018). "At one week following stroke GM-CSF, IL-1β, and IL-5 were reduced, and MIP-1α and MIP-1β were increased in the infarct of the OPN-/- mice." (PMID 30417081, 2018). "In an animal stroke model, icariin pretreatment reduced cytokine levels (IL-1β and TGF-β1), decreased a neurological deficit score, and reduced the infarct volume." (PMID 29382106, 2018). "The current study demonstrated that post-stroke WBV reduces pro-inflammatory cytokine IL-1β and inflammasome proteins in the brain in middle-aged female rats." (PMID 30217051, 2018). "Studies have shown that TNF-α, IL-1β, and IL-6 expression is elevated 0.5, 6, and 3.5 h after stroke, respectively." (PMID 30001721, 2018). "We found that EP4 receptor activation with L-902,688 potently reduces levels of some of the key mediators of stroke-induced BBB damage including IL-1β, IL-6, MMP-3, and MMP-9." (PMID 29527151, 2018).
Stroke (continued). "As the most studied cytokines in adult stroke, IL-1β and TNF-α have been found to exacerbate brain damage by directly inducing neuronal injury and via consequent production of additional cytokines/chemokines and upregulation of adhesion molecules." (PMID 30405724, 2018). "The inhibition of IL-1β signaling with IL-1ra has been found to be protective in experimental models of stroke." (PMID 28115020, 2017). "Stroke induces rapid microglial activation and promotes the secretion of a variety of inflammatory mediators including IL-1β, TNF-α, and IL-6." (PMID 29202856, 2017). "IL-1β is also known to play a significant role in the pathogenesis of type-1 diabetes, acute neurodegeneration, stroke, tumour angiogenesis and invasiveness, and destructive joint and bone diseases." (PMID 29073178, 2017). "In the process of stroke, I/R induced the production and secretion of apoptosis and such inflammation associated cytokines as TNF-α, IL-1β and IL-6." (PMID 29383171, 2017). "For example in experimental stroke, systemic IL1β challenge results in matrix metalloproteinase 9-induced BBB disruption, larger infarct size and poorer neurological outcome." (PMID 27810376, 2017). "The inflammatory response elicited by stroke is orchestrated as a continuum, driven by both activated microglia and infiltrating leukocytes, both known producers of interleukin-1β (IL-1β)." (PMID 26860727, 2016). "In stroke mice, levels of IL-1β level were significantly higher in the XXF vs. XYF group and this was also seen in the XXM group, which had significantly higher IL-1β levels than either XYM or XYwt group." (PMID 27405096, 2016). "Therapeutic injection of IL-1Ra-producing BM cells post-stroke amplified microglial production of IL-1Ra and reduced brain levels of IL-1β, collectively leading to smaller infarcts and improved functional outcome." (PMID 26860727, 2016). "Evidence suggests that the archetypal pro-inflammatory cytokine, interleukin-1beta (IL-1β), is a key component in the pathogenesis of stroke, Alzheimer’s disease (AD) [for review, see 1] and Parkinson’s Disease (PD) [for review, see 2]." (PMID 26989349, 2016). "In anti-stroke target analysis of the total group, the results showed that IL1B, IL8, JUN, MMP9 and PTGS2 were significantly up-regulated." (PMID 27672514, 2016). "Modulating the function of TNF-α and IL-1β has remarkable effects on evolution of the infarct in both experimental and human stroke at the early phase of stroke, corresponding to the therapeutic window (<4.5 h)." (PMID 27688603, 2016). "With this clinical success has come a barrage of research using this anti-IL-1β antibody with much interest in its use in neonatal onset inflammation disease, type II diabetes and stroke." (PMID 25705177, 2015). "IL-1β and TNF-α have been associated with exacerbation of injury in stroke while IL-6 has been found to be neuroprotective." (PMID 26074992, 2015). "The assembly of inflammasomes is required for the processing and secretion of pro-inflammatory cytokines, such as IL-1β, which has been shown to contribute to pathological diseases such as cancer, diabetes, dementia, and stroke." (PMID 26690125, 2015). "Generally, expressions of the cytokines were increased soon after stroke and peaked at 24 h (IL-1β, IL-6, TNF-α) or 48 h (iNOS) post-MCAO." (PMID 25889216, 2015). "The mRNA levels of IL-1β and IL-6 in infarct-side brain tissue were increased on day 1 and decreased on day 4 after stroke onset." (PMID 26059659, 2015). "This improvement in angiogenesis post-stroke following IL-1β treatment has also been seen in endothelial progenitor cell (EPC) cultures." (PMID 25705177, 2015). "Acute neuronal injuries, such as stroke or TBI, cause a rapid up-regulation of IL-1β, IL-1Ra, IL-1 receptor (IL-1R) I, and IL-1RII expression in rats." (PMID 25705177, 2015).
Stroke (continued). "Analysis of pro-interleukin(IL)-1β mRNA after MCAO did not reveal a significant alteration between MT-II treated and vehicle-only treated mice after stroke (relative IL-1β expression 72h after 30min MCAO: vehicleMCAO 4 ± 1.5; MT-IIMCAO: 4.4 ± 1.3; p = n.s.)." (PMID 26658636, 2015). "When mice were treated with ibrutinib or PBS on day 0, mature IL-1β protein levels on day 1 after stroke onset were much lower in the brain lysates of ibrutinib-treated mice than in control mice, whereas the IL-6 and TNF-α protein levels were similar." (PMID 26059659, 2015). "IL-1β and IL-6 stimulate Th17 and Treg cell differentiation, and circulating levels of these cytokines in the acute phase after stroke predict the severity of PSF and poststroke depression (PSD) months thereafter." (PMID 26166952, 2015). "It has been known for some time that inhibition of IL-1β signalling, downstream of inflammasome activation, is an effective means to decrease the size of infarction and improve function after stroke in experimental animal models." (PMID 26690125, 2015). "The type of inflammasomes involved in the inflammatory response and, thus, in the production of IL-1β and IL-18 after stroke is slowly being unravelled." (PMID 26690125, 2015). "In experimental stroke, IL-1β expression increases following brain ischemia and multiple studies have shown that blocking IL-1β can be neuroprotective." (PMID 26473731, 2015). "Exogenous administration of recombinant IL-1β, either centrally or systemically, alongside experimental stroke in rodents leads to an exacerbation of ischemic damage." (PMID 25705177, 2015). "In this study, the mRNA expressions of inflammatory cytokines TNF-α, IL-1β, iNOS, and IL-6 in ipsilateral brain cortex were detected at different time points after stroke." (PMID 25889216, 2015). "The expression of IL-1β significantly increased in the penumbra region 24 hr after stroke, and this elevated level sustained at least until 3 days after stroke." (PMID 26391329, 2015). "Further it is known that IL-1β can induce the expression of iNOS and that iNOS can influence stroke-induced cellular damage." (PMID 26473731, 2015). "The expression of TNF-α, MIP1, Iba-1, and IL-1β were significantly lower in the aLA group than in the control group at 7 days after stroke (P < 0.05)." (PMID 25761600, 2015). "Especially IL-1β is actively produced and released in stroke in tattered neurons and activated microglia by activation of inflammasomes and apoptotic pathways in the hypoxic brain." (PMID 25671080, 2014). "On the basis of these results, we conjectured that morroniside regulated cerebrovascular permeability after stroke via the downregulation of MMPs and IL-1β, hence inhibiting edema formation during the initial phase." (PMID 24979385, 2014). "We observed that the IL-23, IL-6, and IL-1β plasma levels were increased in IS patients at 7 and 28 days after stroke compared with controls." (PMID 24991091, 2014). "TNF-α and IL-1β are two well-studied cytokines involved in inflammatory responses after stroke and appeared to aggravate ischemic damage." (PMID 23762140, 2013). "In Alzheimer’s disease, stroke and brain injuries, activated microglia can release proinflammatory cytokines, such as interleukin (IL)-1β." (PMID 23651534, 2013). "This is particularly true after an acute brain injury such as cerebral ischemia, or stroke, where IL-1β is established as a major contributor to damage." (PMID 23024646, 2012). "In this condition, the administration of IL-1β significantly accelerated the onset of stroke compared with control (P = 0.006), even though administration of IL-1β did not affect blood pressure." (PMID 23326018, 2012). "There was a significant inverse correlation between plasma IL-1β level and the day of stroke onset in all rats (r = −0.600 [P = 0.007])." (PMID 23326018, 2012).
Stroke (continued). "Inhibition of IL-1β activity or signaling with antibodies neutralizing cytokines or soluble cytokine receptors decreased neuronal damage in animal models of stroke." (PMID 22806180, 2012). "Upon brain ischemia, microglia/macrophages release inflammatory cytokines such as TNF-α and IL-1β in models of stroke." (PMID 23028794, 2012). "In this study we sought to determine the spatial distribution of IL-1α and IL-1β in the mouse brain early (4 h) and late (24 h) after stroke induced by MCAo." (PMID 22206506, 2011). "The most prominent ones after stroke are interleukin-1β (IL-1β), tumor necrosis factor-α (TNF-α) and IL-6." (PMID 21040547, 2010). "The JNK pathway can be intensely activated by factors such as TNF-α and IL-1β, which are known to be increased after a stroke and have been shown to be involved in the mechanisms underlying ischemia-induced neuron apoptosis." (PMID 23554623, 2010). "For instance, IL-1β is rapidly induced in experimental models of stroke and mice that have decreased IL-1 production are significantly protected from ischemic injury." (PMID 16808851, 2006). "Compared with controls, stroke patients exhibited lower circulating IL-1β and higher IL-1Ra." (PMID 41301455, 2025). "Here we show that IL-1α and IL-1β have different spatio-temporal expression profiles in the brain after experimental stroke, with early microglial IL-1α expression (4 h) and delayed IL-1β expression in infiltrated neutrophils and a small microglial subset (24-72 h)." (PMID 40110693, 2025). "Furthermore, a longitudinal study indicated that elevated levels of TNF-α and interleukin-1 beta (IL-1β) within 2 weeks post-stroke are strongly correlated with the occurrence of PSD." (PMID 41458124, 2025). "This divergence may reflect rapid IL-1β consumption, short-lived systemic peaks relative to longer-lived IL-1Ra, post-stroke immune reprogramming, and sampling timing." (PMID 41301455, 2025). "C24:1 nervonic acid showed an inverse correlation with IL-1β in stroke patients." (PMID 41301455, 2025). "Among fatty acids, the strongest positive correlations with IL-1β in our early subacute phase of stroke cohort were observed for C15:0 pentadecanoic acid and C15:1 cis-10 pentadecanoic acid, with C15:0 pentadecanoid acid remaining significant after multivariate analysis." (PMID 41301455, 2025). "The release of IL-1β after stroke induces persistent proinflammatory changes in monocytes/macrophages, causing multiorgan damage, most notably myocardial fibrosis and dysfunction, in both mice with MCAO and stroke patients." (PMID 40618510, 2025). "After stroke, microglia undergo significant morphological changes, from small branching structures to large amoeba-like structures, that produce pro-inflammatory factors, including IL-1β, IL-6 and TNF-α." (PMID 40004043, 2025). "IL-1B can directly lead to hepatocyte injury by activating apoptotic and necrotic pathways, and in some neuropathies, such as stroke and Alzheimer’s disease, the overexpression of IL-1B may promote neuronal apoptosis and lead to neurological dysfunction." (PMID 40238193, 2025). "Studies have revealed that the NF‐κB signaling pathway is over‐activated in microglial cells following a stroke, serving as a crucial regulator of the inflammatory response by driving the transcription of downstream pro‐inflammatory cytokines such as IL‐1β, TNF‐α, and IL‐6." (PMID 40237440, 2025). "This cascade effect explains why inflammatory factors (e.g., TNF-α, IL-1β) are commonly elevated in both Osteoporosis and stroke patients, and also provides a molecular basis for the “inflammation as a common pathological basis” hypothesis of comorbidity." (PMID 41379792, 2025). "IL-1β is the predominant form expressed in the brain and is upregulated following stroke." (PMID 41301455, 2025).